IL9 (interleukin 9)
Diseases named in the same sentence as IL9 in open-access papers (continued):
Sharing a sentence is not in itself a finding about the gene and the disease.
helminth infections (continued). "More recently, using IL-9-fluorescent reported mice, it has been shown that Th9 and type 2 innate lymphoid cells (ILC2s) were major sources of worm infection-induced IL-9 production." (PMID 25259859, 2014). "In line with recent data suggesting that IL-9 plays a fundamental role in control of helminth infection and pathology, we confirm that IL-9 is central for control of S. ratti infection in both, BALB/c and C57BL/6 mice." (PMID 24516385, 2014). "In chronic human and experimental infections, Schistosoma mansoni, like all helminth infections, induces a predominantly Th2 immune response, characterized by interleukin-4, IL-5, IL-9, IL-10 and IL-13, antibody (IgE and IgG4), eosinophils and mast cells." (PMID 23849678, 2013). "Further, helminth infections induce the production of Th2 related cytokines, such as IL-4, IL-5, IL-9 and IL-13, with anti-inflammatory qualities." (PMID 23782752, 2013). "As helminthiasis, atopy is the result of aberrant Th2 cytokine response to allergens, with an increased production of IL-4, IL-13, Il-9 and Il-5, with high amounts of allergen-specific and total IgE and eosinophilia." (PMID 19471606, 2008). "Our findings in an animal model as well as human data suggest that the protective effect of helminth infection on insulin resistance and obesity might be partly mediated by IL-9 signaling." (PMID 40962954, 2025). "In addition, we also demonstrate a role for IL-9 in the protective effects of helminth infection during obesity and insulin resistance." (PMID 40962954, 2025). "However, IL-9, a classic type 2 cytokine, has been relatively well studied in the context of allergic immune responses, parasitic helminth infections and autoimmune diseases." (PMID 40962954, 2025). "Helminth infection’s faster expulsion from gastrointestinal tract is enhanced by IL-9." (PMID 33213045, 2020). "IL-9 plays a fundamental role in the control of helminth infection and pathology." (PMID 32243446, 2020). "The deletion of either BTLA or its ligand finally elevated IL-9 production and reduced parasite burden in S. ratti-infected C57BL/6 mice, thus suggesting that additional regulatory pathways suppressed IL-9 production during helminth infection on this genetic background." (PMID 29872093, 2018). "Therefore, IL-9 has the ability to act as a critical cytokine in mucosal infections especially helminth infections and indeed, has been shown to be crucial driver of the host immune response against these infections in animal models." (PMID 26730582, 2016). "Furthermore, Th9 cells, through the expression of the effector cytokine IL-9, are more efficient than classical Th2 cells at orchestrating antihelminthic responses in helminthic infection in vivo." (PMID 26509179, 2015). "Thus, IL-9 might be a factor responsible for the protective effect of helminth infection during diabetes." (PMID 40962954, 2025). "IL4 has distinct functions in helminth infections but there is considerable redundancy with IL13, IL5 and IL9, whose contributions also vary among systems and parasite species/strains." (PMID 33226981, 2020). "IL-9 functions as a central autocrine survival factor for ILC2 that initiate and amplify the adaptive type 2 immune response during helminth infection and allergic inflammation via production of IL-13 and IL-5, as demonstrated in C57BL/6 mice." (PMID 29872093, 2018). "The role of CD4+ and CD8+ T cell subset distribution and the association between memory T cell subsets and the common γc cytokines (IL-2, IL-4, IL-7, IL-9 and IL-15) in helminth infections has not been explored well." (PMID 29795573, 2018). "However, the effects of helminth infection on common γc cytokine—IL-2, IL-4, IL-7, IL-9 and IL-15- levels have not been explored in Ss infection." (PMID 29795573, 2018).
helminth infections (continued). "However, a more recent study has clearly shown that IL-9 is produced early during Nippostrongylus brasiliensis infection of mice by a non-Th2 CD4+ T cell subset and that its production from this subset is sufficient for host protection against worm infection." (PMID 26730582, 2016). "In a helminth infection model, mice lacking CCR8 exhibit reduced type 2 cytokines IL-5, IL-13, and IL-9, and greater worm burden in the small intestine." (PMID 35707544, 2022). "To confirm whether type 2 cytokines IL-4, IL-5, IL-9, and IL-13 contributed to helminth-induced protection against TNF-α and IFN-γ shock, we compared the levels of cytokines in the presence or absence of the helminth infection." (PMID 38727220, 2024).
allergic asthma (31 papers, 2005 to 2026). A asthma with a basis in a pathological type I hypersensitivity reaction. "The majority of patients with allergic asthma suffer from a type 2 immune response, which is associated with Th2-mediated cytokines, including IL-4, IL-5, IL-9 and IL-13." (PMID 35744915, 2022). "In an allergic asthma model, mice with a deficiency of Itk showed reduced pulmonary inflammation and IL-9 production by T cells." (PMID 33748292, 2021). "Classically, IL-9 has been considered a Th2 cytokine and has been implicated in allergic asthma and parasitic infections." (PMID 31216735, 2019). "In bronchial biopsies, the cells expressing IL-9, which were predominantly T cells, were increased in patients with allergic asthma, and this was associated with bronchial hyper-reactivity." (PMID 15840176, 2005). "Th9 cells produce interleukin (IL)-9, a cytokine implicated in allergic asthma and autoimmunity." (PMID 26936133, 2016). "Like IL-4, IL-9 is associated with type II immune responses, such as in allergic asthma." (PMID 26936133, 2016). "There is evidence in clinical studies for an association between IL-9 and allergic asthma." (PMID 15840176, 2005). "The expression of IL‐9 was also found to be elevated in peripheral blood mononuclear cells (PBMCs) derived from patients with allergic asthma." (PMID 41568067, 2026). "In allergic asthma, IL-9 drives inflammation, while in specific tumor microenvironments, IL-9 can exert anti-tumor effects." (PMID 40948790, 2025). "As Th9 cells contribute to allergic inflammation via IL-9 secretion, modulating this pathway through miRNA-based strategies presents a promising avenue for allergic asthma management." (PMID 40806181, 2025). "Allergic asthma, which is common in childhood, exhibits a T2-high response with activation of IL-4, IL-5, IL-9, or IL-13, accompanied by eosinophilic inflammation." (PMID 40867700, 2025). "Epigenetic regulation of IL-9 is seen in murine models of allergic asthma, autoimmunity, antihelminth defense, and antitumor immunity." (PMID 38825637, 2024). "Inhibition or deletion of Foxo1 can reduce IL-9 production by Th9 cells and significantly improve the inflammatory response in allergic asthma." (PMID 35935994, 2022). "High frequency of IL-9+ CD8 T cells (Tc9) have been associated with eosinophilia and high fractioned exhaled nitric oxide of allergic asthma." (PMID 34884454, 2021). "IL-9 is believed to have a mediating role in the pathogenesis of allergic asthma, especially in the mast cell component." (PMID 31395084, 2019). "The type 2 cytokines, interleukin- (IL-) 4, IL-5, IL-9, and IL-13, are the major drivers of allergic asthma and studies." (PMID 31737687, 2019). "Clinically, the peripheral blood of patients with allergic asthma has been found to contain higher Th9 cell and IL-9 concentrations than healthy subjects." (PMID 31216735, 2019). "In this study, we found that PBMCs from children with allergic asthma produced and secreted higher levels of Th2-specific cytokines IL-4, higher levels of IL-9, and lower levels of Th1-specificcytokine IFN-γ compared to healthy children." (PMID 28724400, 2017). "In our present work, we demonstrate that IL-9, which is mainly produced by Th9 cells in children with allergic asthma, impairs IFN-γ production and synergistically promotes IL-4-induced IgE secretion." (PMID 28724400, 2017). "Compared with healthy children, HDM extract induced higher levels of IL-9 production in children with allergic asthma." (PMID 28724400, 2017). "Consistently, IRF1 restricts the IL-9-dependent pathogenicity of Th9 cells in a mouse model of allergic asthma." (PMID 28497800, 2017). "In conclusion, our studies showed that high level of IL-9 in children with allergic asthma was mainly produced by Th9 cells, instead of Th2 cells." (PMID 28724400, 2017).
allergic asthma (continued). "Levels of IL-9 and IL-4 in children with allergic asthma(30.23 ± 1.92 pg/ml and 25.81 ± 2.14 pg/ml, respectively) were significantly higher than those in healthy children (67.37 ± 9.27 pg/ml and 49.50 ± 9.99 pg/ml, respectively)." (PMID 28724400, 2017). "Then isolated PBMCs from 5 healthy children and 5 children with allergic asthma were stimulated with 10 μg/ml HDM extract at the concentration of 2 × 106cells/ml for 48 h.IL-9 levels in the supernatants were tested by ELISA." (PMID 28724400, 2017). "After stimulation with PMA plus ionomycin in the presence of BFA, intracellular staining showed that PBMCs from children with allergic asthma expressed higher level of IL-9." (PMID 28724400, 2017). "In view of the reduced IFN-γ levels and increased IL-9 levels by PBMCs from children with allergic asthma, we investigated the function of IL-9 on the production of IFN-γ by Th1 cells." (PMID 28724400, 2017). "Our results showed that peripheral blood mononuclear cells (PBMCs) from children with allergic asthma produced higher levels of IL-9 and IL-4 and lower levels of IFN-γ than healthy children." (PMID 28724400, 2017). "Here the authors show in human cells and mouse models that Itk is also needed for the production of IL-9, an important contributor to allergic asthma." (PMID 26936133, 2016). "In allergic asthma patients, IL-9 in the bronchoalveolar fluid was increased after segmental allergen challenge." (PMID 15840176, 2005). "Additionally, IL‐9 is involved in MCs′ proliferation and migration, which serves as a pivotal factor in the pathogenesis of allergic asthma." (PMID 41568067, 2026). "IL-9 is produced by CD4 + T cells, in particular Th2 cells, and is associated with allergic asthma." (PMID 39061002, 2024). "The importance of IL-9-mediated Arg1+ macrophages in allergic asthma has been recently reported." (PMID 38162655, 2023). "Furthermore, IL-9 signaling in the mucosal immune system is mainly present in allergic asthma, inflammatory bowel diseases, and other conditions." (PMID 36986757, 2023). "In addition, T-Dusp8–cKO mice displayed reduction of IL-9 and Th9-mediated immune responses in the allergic asthma model." (PMID 37909329, 2023). "The effector functions of Th9 cells in allergic airway inflammation can be attributed to not only the production of the signature cytokine IL-9 but also the utilization of other lymphoid cell types which may have various roles in allergic asthma." (PMID 33748292, 2021). "In addition, we tried to shed light on the relationship between NFATc1 and NFATc2 and IRF4, another transcription factor upregulating cytokines like IL‐4 and IL‐9 involved in allergic asthma." (PMID 33079489, 2020). "Both IL-4 and IL-9 are known to shape the immune response in allergic asthma." (PMID 31703379, 2019). "In conclusion, our results showed that Th9 cells may be the major source of IL-9 in children with allergic asthma." (PMID 28724400, 2017). "Considering the important role of IL-9 that may plays in the immune response, determining the major source of IL-9 will further increase our understanding of the pathogenesis of allergic asthma." (PMID 28724400, 2017). "Furthermore, our results demonstrated that exogenous IL-9 inhibited IFN-γ production by PBMCs or purified CD4+ T cells from children with allergic asthma in a dose-dependent manner." (PMID 28724400, 2017). "Together, these findings indicate that high level of IL-9 in children with allergic asthma may be produced by Th9 cells, instead of Th2 cells." (PMID 28724400, 2017). "Interleukin-9 (IL-9) was reported as an active participant in the pathogenesis of allergic asthma." (PMID 28724400, 2017). "Several animal studies have investigated the role of IL-9 in allergic asthma." (PMID 15840176, 2005). "Despite the findings in knock-out mice, overall the evidence from animal models is consistent with clinical evidence that IL-9 may have a role in allergic asthma." (PMID 15840176, 2005).
allergic asthma (continued). "Specifically targeting DCs to modulate CD4+ T cell responses may represent a promising approach to treat allergic asthma where an enhanced Th2 response frequently leads to IgE production (IL-4), eosinophilia (IL-5), mast cell activation (IL-9), and AHR (IL-13)." (PMID 28439267, 2017). "Results showed that compared with healthy children, levels of IL-9, IL-4 and PU.1 were elevated and levels of IFN-γ were lower in children with allergic asthma." (PMID 28724400, 2017). "We first detected the production of IL-9 and IL-4, and IFN-γ by PBMCs from children with allergic asthma compared with healthy children of similar age." (PMID 28724400, 2017). "Up-regulation of IL-9 production and down-regulation of IFN-γ production by mononuclear cells were detected in children with allergic asthma." (PMID 28724400, 2017). "Results also showed higher production of transcription factor PU.1 and house dust mite (HDM)-specific IL-9-expressing cells, indicating that Th9 cells but not Th2 cells are the major source of IL-9 in allergic asthma." (PMID 28724400, 2017). "Intracellular staining analysis further showed that HDM induced high percentages of IL-9-expressing CD4+ T cells (0.045 ± 0.008%) in children with allergic asthma, but not in healthy children." (PMID 28724400, 2017). "Studies using adoptively transferred models of allergic asthma demonstrated that exogenously or ectopically expressed proallergic cytokines such as TSLP, TNF family cytokine TLI1 (Tnfsf15), and IL-25 promoted airway inflammation by increasing Th9 cell differentiation and IL-9 production." (PMID 33748292, 2021). "However, in a model of allergic asthma, airway hyperreactivity, eosinophilia and goblet cell hyperplasia were not impaired in IL-9 knock-out mice." (PMID 15840176, 2005). "Accordingly, the absence of IRF1 in IFN-γ-treated Th9 cells led to increased IL-9-dependent pathogenicity in AAD, a mouse model for allergic asthma." (PMID 28497800, 2017). "Purified CD4+ T cells were separated from PBMCs of children with allergic asthma, and were stimulated with plate-coated anti-CD3 in the presence or absence of 20 ng/ml IL-9 for 3 days, the concentration of IFN-γ in the supernatants were then detected by ELISA." (PMID 28724400, 2017). "In addition, IL-9-expressing CD4+ T cells did not co-express IL-4, indicating that large percentage of IL-9-expressing CD4+ T cells in children with allergic asthma might be Th9 cells in origin, instead of Th2 cells." (PMID 28724400, 2017).
psoriasis (31 papers, 2012 to 2025). An autoimmune condition characterized by red, well-delineated plaques with silvery scales that are usually on the extensor surfaces and scalp. "Although Th17 cells and IL-17 were reported to be involved in the pathomechanism of BP, this study showed that Th17 cells rarely produced IL-9 in the blister fluid of BP, suggesting that the pathogenic role of IL-9 differs between BP and psoriasis." (PMID 37398641, 2023). "Elevated Th9 and IL-9 levels in the serum or tissues of patients with psoriasis and rheumatoid arthritis are associated with disease severity and the duration of inflammation." (PMID 35935994, 2022). "Examples are accumulation of granulocytes stimulated by IL-8, IL-17, IL-9 and IL-13; epidermal hyperplasia and psoriasis-like skin lesions due to IL-22; and fever and weight loss in response to IL-6 and IFN-γ." (PMID 34503066, 2021). "The cytokine IL-9 is involved in chronic inflammation and has recently been associated with psoriasis." (PMID 30013558, 2018). "While, near the IL-9 gene locus on chromosome 5q31.1-q33.1 is a psoriasis susceptibility gene." (PMID 40690118, 2025). "In addition, IL-9 is also increased in psoriasis patients, which not only promotes Th17-associated inflammation and angiogenesis in psoriasis, but also facilitates P-selectin expression and platelet activation via JAK2/STAT3 pathway in deep venous thrombosis." (PMID 37654493, 2023). "Recently, the association between IL-9 and the Th17 pathway has been reported in psoriasis." (PMID 32210952, 2020). "hTGF-b1 transgenic mice, suggesting that there is a pathogenic involvement of IL-9 in psoriasis." (PMID 31035677, 2019). "IL-9 has been associated with increased IL-17A production in an animal model of psoriasis." (PMID 30013558, 2018). "Together these observations and the location of IL-9 gene on chromosome 5 (5q31.1), a psoriasis susceptibility region (5q31.1-q33.1), prompted us to investigate the pathogenic role of IL-9 in psoriasis." (PMID 23335955, 2013). "Excessive production of IL-9 may be linked to the hyperactivation of immune cells and dysregulated inflammatory responses, therefore contributing to the etiology of inflammatory skin conditions, especially psoriasis." (PMID 40303401, 2025). "To additionally explore the possible role of IL-9 in AD, we have used an ex vivo coculture system made of patient’s purified circulating memory T cells and autologous lesional epidermal cells that has previously enabled the association of T-cell functions with clinical features in AD and psoriasis." (PMID 39201262, 2024). "Collectively, both patients with psoriasis and psoriatic animal models show an excessive expression of IL-9 and IL-9R and an altered frequency of Th9 cells, suggesting that IL-9 promotes psoriasis and PsA development." (PMID 40771819, 2025). "IL-9-mediated crosstalk: Elevated IL-9 levels in psoriasis patients with MetS comorbidity suggest its potential role as a molecular link between inflammatory and metabolic pathways." (PMID 40385577, 2025). "The inflammatory cytokines IL-17, IL-22, and IL-9 are generated by these cells and play a role in the development of psoriasis." (PMID 40690118, 2025). "Nevertheless, several studies also observed a significant increase in eosinophils and cytokines, such as IL-4, IL-5, IL-9, IL-31, and IL-33, among others, in the blood of patients with psoriasis." (PMID 36865550, 2023). "There are numerous other cytokines and pathways acting as a promoter in the pathogenesis of psoriasis, such as IL-9." (PMID 38008779, 2023). "Among skin diseases, it was reported that the patient’s skin with psoriasis expressed a higher number of IL-9R–positive cells and the patient’s skin with atopic dermatitis expressed higher IL-9 mRNA compared with the normal skin." (PMID 37398641, 2023).